GPX1 (glutathione peroxidase 1)
Diseases named in the same sentence as GPX1 in open-access papers (continued):
Sharing a sentence is not in itself a finding about the gene and the disease.
selenium deficiency (24 papers, 2011 to 2025). A nutritional deficiency disease resulting from inadequate selenium levels in the body, which can lead to impaired function of selenoproteins essential for antioxidant defense and thyroid hormone metabolism. "In WT mice, selenium deficiency resulted in decreased serum SeP, reduced selenium concentrations, and lowered hepatic GPx1 expression." (PMID 40818321, 2025). "During selenium deficiency, the activity of liver GPX1 in rats drops to 3% of its normal activity, whereas the activity of GPX4 is better maintained." (PMID 38990713, 2024). "During times of selenium deficiency, the expression of certain selenoprotein genes such as GPX1, GPX3, and selenoprotein W (SELENOW) are more sensitive and thus downregulated compared with “housekeeping” selenoproteins such as deiodinases (DIOs) and GPX4." (PMID 39270936, 2024). "This phenotype in GPx-1-overexpressing mice can be almost completely reversed under dietary selenium deficiency or alleviated with reduced food intake by 40%." (PMID 39469571, 2024). "GPX-1 is one of the selenoproteins whose levels decrease the most in selenium deficiency, making it susceptible to selenium status." (PMID 35215475, 2022). "The observation of prioritized GPX4 expression at the expense of low-hierarchy selenoproteins, such as glutathione peroxidase 1 under selenium deficiency, suggests that GPX4 plays essential roles in the prevention of membrane oxidation." (PMID 35204181, 2022). "Many researchers demonstrated a marked reduction in the expression of GPX1 in selenium deficiency highlighting the possibility that ovarian pathologies can be improved through its integration." (PMID 35353297, 2022). "It has been shown that GPx-1 expression is diminished by selenium deficiency both in vitro and in vivo studies." (PMID 34829616, 2021). "In a study it was demonstrated that follicular selenium deficiency reduced glutathione peroxidase-1 expression." (PMID 34568729, 2021). "In rat hearts, selenium deficiency has also been associated with decreased expression in both TrxR, as well as GPx1, impairing ischemia-reperfusion recovery." (PMID 32210049, 2020). "Selenium deficiency leads to down-regulation of GPx1 and catalase and increased production of mucosa and altered epithelial morphology." (PMID 30049972, 2018). "Clinical studies suggest an extra layer of complexity surrounding Keshan disease on account of decreased GPx1 activity in individuals with both selenium deficiency and a specific leucine-containing GPx1 allele." (PMID 26664900, 2015). "Selenium deficiency affects the expression of selenoenzymes such as GPx1, GPx2, and GPx4 and selenoproteins (i.e., Selenoproteins-P, SELENOP), which are involved in not only fetal reproductive development and the regulation of oxidative stress but also the overall DNA methylation pattern." (PMID 37233634, 2023). "Both selenium deficiency and GPx1 knockout heightened inflammatory responses and more severe lung pathology in response to influenza A infection, further indicating that GPX1 participates in molecular mechanisms protecting against viral infections of the respiratory tract." (PMID 35563199, 2022). "Such decrease of GPx1 can also result from selenium deficiency." (PMID 30049972, 2018). "Interestingly, several genes encoding selenoproteins (GPX1, GPX4, SELENON, SELENOM, SELENOF, SELENOW, SELENOT) were also downregulated, suggesting molecular evidence of selenium deficiency." (PMID 40459789, 2025). "Under the condition of selenium deficiency, the activities of GPX and TR in liver and intestine of germ-free (GF) mice were higher than those of conventionalized (CV) mice, and the expression of GPX1 and its mRNA in liver and colon were also higher." (PMID 34484164, 2021). "There were no changes observed in either GPx1 or GPx3 expression in the livers and hearts of foetuses due to maternal selenium deficiency." (PMID 32210049, 2020).
selenium deficiency (continued). "So in selenium deficiency, Sec incorporation complex is not formed and GPx1 mRNA does not get translated." (PMID 25168993, 2014). "The mechanism of decreased GPx1 in CD-derived macrophages is unknown and was found to be independent of selenium deficiency." (PMID 39695083, 2024). "In selenium deficiency cases, GPX1 mRNA may be degraded via NMD when the Sec-tRNAs were not sufficient enough to continue protein translation." (PMID 31109102, 2019). "This elongation factor (eIF4a3) is induced in selenium deficiency and binds to type-1 SECIS elements, which is SECIS in GPx1 but not in GPx4." (PMID 25168993, 2014).
lung carcinoma (22 papers, 2008 to 2025). "The rs1050450 in GPX1 has been shown to be associated with an increased lung cancer risk in one study, but others suggests a reverse correlation." (PMID 30640897, 2019). "The influence of rs1050450 in GPX1 on lung cancer risk have been already analyzed in several studies, but results were inconsistent." (PMID 23516596, 2013). "Stronger association between smoking, alcohol intake and lung cancer was seen in carriers of the genotype TT of GPX1(Pro200Leu) than in carriers of genotype CC." (PMID 18298806, 2008). "It is reported that the GPX1 polymorphism (Pro198Leu, rs1050450) may contribute significantly to lung cancer risk." (PMID 32648197, 2021). "Frequent loss of heterozygosity (LOH) on chromosome 3p in lung tumors was associated with low GPx1 enzyme activities, which may affect the prognosis of lung cancer patients." (PMID 32571353, 2020). "GPX1 SNP rs1050450 is found to influence the risk of lung cancer and bladder cancer." (PMID 26881045, 2016). "That individuals with GPX1 679T/T alleles showed significantly lower plasma Se levels than those of the C/C alleles is of particular interest, as the former genotype has been associated with increased risk to cancers of the lung and breast." (PMID 21767397, 2011). "To test our hypothesis above and to determine the role of ROS in GPX1 associated resistance to cisplatin in lung cancer, we compared the dynamic changes of intracellular ROS levels with and without exogenous overexpression of GPX1 gene in cisplatin sensitive cell lines H460 and H1650." (PMID 31032363, 2019). "Previous reports demonstrated that anti-GPX-1 (Abcam, ab22604; employed in this study) stained distinct cells in formalin-fixed tissue sections from lung carcinoma." (PMID 40059238, 2025). "Fumarate can activate GPX1 to perturb redox homeostasis and promote cell proliferation of breast and lung cancer cells." (PMID 35626163, 2022). "Since GPX1 plays a fundamental role in metabolizing intracellular ROS and maintaining hemostasis of cells, it is reasonable to hypothesize that elimination of ROS induced by cisplatin treatment may be the associated mechanism for GPX1 induced resistance to cisplatin in lung cancer." (PMID 31032363, 2019). "The rs4880 in SOD2 and rs1050450 in GPX1 were previously tested in lung cancer patients, however the results were inconclusive." (PMID 30640897, 2019). "Individuals with reduced GPX1 activity exhibit an increased incidence of oxidative stress-related diseases such as breast, colon, prostate, bladder and lung cancers, coronary artery disease, and also, low bone mineral density and osteoarthropathy." (PMID 28052094, 2017). "This suggested that GCLC and GPX1 genes may be used as biomarkers of bad prognosis in people with lung cancer, even with different genetic backgrounds." (PMID 32850411, 2020). "In another study, serum selenium levels were determined in 95 patients with lung cancer and the genotypes of four selenoprotein genes (GPX1, GPX4, TXNRD2, and SEP15) were determined, demonstrating that a selenium level less than 60 μg·L−1 is associated with a higher risk of lung cancer." (PMID 30759767, 2019). "The reduced expression of GPx1 in lung cancer contributes to malignant transformation." (PMID 30538220, 2018). "However, this study provides some support for the T-Allel of GPX1(Pro200Leu) and the C-Allele of EPHX1(His113Tyr) to play a protective role in early onset lung cancer susceptibility." (PMID 18298806, 2008). "However, decreased expression of “GPX1” (OR 2.35; 95% CI 1.63–3.39; P = 5.42 × 10−6) and “THBS3” (OR 1.50; 95% CI 1.30–1.73; P = 3.30 × 10−8) were found to be associated with the higher risk of lung cancer and gastric cancer." (PMID 38659038, 2024). "As a result of these observations, we postulate that GCLC, GPX1 genes and glutathione metabolism are possible targets to delay EMT or potentially prevent the EMT in lung cancer." (PMID 32850411, 2020).
lung carcinoma (continued). "A previous study suggests that GPX1 may induce cisplatin-based chemoresistance in NSCLC, but the exact role of this gene in lung cancer is still unclear." (PMID 37511126, 2023). "Analyzing survival data of men with lung cancer, we observed that patients with mutations in GCL catalytic subunit (GCLC) or Glutathione peroxidase 1 (GPX1) genes survived less time than people without mutations on these genes." (PMID 32850411, 2020).
coronary artery disease (21 papers, 2007 to 2025). "In a case-control study, lower GPx1 activity was associated with coronary artery disease (4.72; 95% CI, 1.61–13.79) and was inversely correlated with severity of disease." (PMID 34579115, 2021). "The GPX1 rs1050450 CT and TT genotypes were reported to be associated with increased risk of damage caused by oxidative stress, such as in coronary heart disease and cancer." (PMID 33803434, 2021). "In a prospective study of >600 patients with suspected coronary artery disease, GPX1 erythrocyte activity was related to the risk of cardiovascular events, independent from smoking status." (PMID 31404994, 2019). "In a prospective study of patients with suspected coronary artery disease, erythrocyte GPX-1 and SOD activity were inversely associated with incidence of cardiovascular events after adjusting risk factors of cardiovascular diseases." (PMID 25243185, 2014). "Accordingly, a low activity of red blood cell GPx-1 is associated with an increased risk of cardiovascular events in patients with coronary artery disease, and carotid atherosclerotic plaques of patients have reduced GPx-1 activity." (PMID 23991041, 2013). "This is particularly relevant since clinical findings have shown that reductions in GPx1 activity have been linked to increased cardiovascular disease, both within a diabetic setting and in association with coronary artery disease." (PMID 23874911, 2013). "Moreover, in coronary artery disease patients, the combination of lowest GPx1 activity and highest plasma homocysteine was associated with the greatest risk for future CV events (HR 3.2; 95% CI, 1.8 to 5.6; p < 0.0001)." (PMID 34579115, 2021). "However, accurate assessment of coronary artery disease (CAD) using GPX-1 polymorphism is limited for South Asian population." (PMID 27229152, 2016). "Thus, the present study was undertaken toassess the association between severity of coronary artery disease with GPX-1 and GPX-1 polymorphism (Pro198Leu) based on new angiography scoring system." (PMID 27229152, 2016). "The presence of Pro197Leu substitution of the GPx-1 gene may play a crucial role in determining genetic susceptibility to coronary-arteriosclerosis in T2D." (PMID 17825092, 2007). "Indeed, recent preclinical and clinical data have shown that GPx1 plays a critical role in protecting the cardiovascular system against oxidative stress with low levels of GPx1 activity acknowledged as an independent risk factor for cardiovascular events in patients with coronary artery disease." (PMID 22013533, 2012). "In addition, it has been found that the presence of Pro197Leu substitution of the GPx-1 gene may play a crucial role in determining genetic susceptibility to coronary-arteriosclerosis in type II diabetic patients." (PMID 23675242, 2011). "Glutathione peroxidase 1 (GPX1) is one of the pivotal antioxidant enzymes in vascular endothelium, which protects against the presence of coronary artery disease." (PMID 25727037, 2015). "Another isoform of glutathione peroxidases is called GPx1, the key antioxidant enzyme in vascular endothelial cells and plays a protective effect against the presence of coronary artery disease [CAD]." (PMID 23675242, 2011). "In human patients with coronary artery disease, red blood cell GPx1 activity was a strong predictor of future cardiovascular (CV) events, with a hazard ratio of 0.29 (95% confidence interval, CI, 0.15–0.58; p < 0.001) for the lowest tertile compared to the highest tertile." (PMID 34579115, 2021). "Glutathione peroxidase-1 (Gpx1) was also evaluated, as decreased erythrocyte Gpx1 activity is associated with increased cardiovascular risk in patients with coronary artery disease; however, no change was seen." (PMID 27805009, 2016). "Besides, selenium supplementation may improve the antioxidant capacity of patients with coronary artery disease (CAD) by increasing GPx-1 activity." (PMID 36699906, 2022).
coronary artery disease (continued). "Present study aim to assess GPX-1activity and GPX-1 polymorphismin patients with coronary artery disease (CAD) who were confirmed with coronary angiography findings and in apparently healthy subjects." (PMID 27229152, 2016). "GPX1 is an antioxidant enzyme that can restore an endothelial phenotype in some types of pathology with high levels of oxidative stress, such as hyperhomocysteinemia, and the activity of GPX1 has been inversely correlated with CVD in patients with coronary artery disease." (PMID 35268023, 2022).
endothelial dysfunction (21 papers, 2012 to 2025). In vascular diseases, endothelial dysfunction is a systemic pathological state of the endothelium (the inner lining of blood vessels) and can be broadly defined as an imbalance between vasodilating and vasoconstricting substances produced by (or acting on) the endothelium. "GPx-1 plays an important role in maintaining endothelial function and NO bioavailability GPx-1 deficiency leads to marked vasoconstriction and forms endothelial dysfunction." (PMID 39861168, 2025). "In homozygous GPx1−/− mice, responses to ACh were impaired in isolated carotid arteries and Gpx1 protects against Ang II-induced endothelial dysfunction, suggesting that elevated levels of H2O2 cause endothelial dysfunction." (PMID 39099341, 2024). "Mice deficient in GPx1 also have increased levels of aortic isoprostanes along with endothelial dysfunction and structural changes in the artery." (PMID 32084149, 2020). "It has been demonstrated that mice that are heterozygous for GPx1 deficiency have endothelial dysfunction combined with structural vascular abnormalities." (PMID 28574428, 2017). "Regarding potential mechanisms mediating the influence of GPx1 deficiency and endothelial dysfunction, it has been shown that GPx1 deficiency apparently decreases bioavailable NO in mice." (PMID 28574428, 2017). "High homocysteine levels are associated with reduced activities of the electron transport chain and increased oxidative stress, and homocysteine-mediated endothelial dysfunction, in part, is associated with a reduction in GPx1, which is ameliorated by GPx1 overexpression." (PMID 38539790, 2024). "Thus, we next examined the effects of ebselen, a GPx-1 mimetic, on endothelial dysfunction caused by CS and IAV infection." (PMID 35343564, 2022). "In addition, GPx1 deficiency has been shown to accelerate angiotensin-II-mediated endothelial dysfunction, cardiac hypertrophy, and mean arterial blood pressure." (PMID 22013533, 2012). "GPx1 has been found to regulate endothelial function, as genetic knockdown of GPx1 promotes endothelial dysfunction, in both heterozygous and homozygous knockout mice." (PMID 34579115, 2021). "It has been reported that a deficit of GPx-1 directly increases oxidative stress levels with consequent endothelial dysfunction." (PMID 26473024, 2015). "Collectively, these studies implicate a major role for GPx1 in protecting the vasculature against hyperglycaemia-mediated oxidative stress, endothelial dysfunction, atherogenesis, and nephropathy." (PMID 22013533, 2012). "Although deletion of GPx1 is nonlethal and GPx1 KO mice are fertile, these mice have an enhanced oxidative stress profile and are more susceptible to endothelial dysfunction." (PMID 22013533, 2012). "Endothelial dysfunction, which was manifested in the form of diminished NO bioavailability, was well compensated for by an increased expression of KCa3.1 protein, as shown in aged wild‐type, CerS2 null, and catalase−/−/GPX1−/− mice, and an upregulation of KCa3.1 channel activity." (PMID 27363720, 2016). "Previously, we established that TRAF6 inhibition partially prevented endothelial dysfunction, weight gain, increase in HbA1c values, oxidative burst of whole blood leukocytes, cardiac RAGE signaling, vascular ROS formation, and impaired catalase/glutathione peroxidase 1 expression in db/db mice." (PMID 38554187, 2024). "Age-related endothelial dysfunction involves upregulation of the NADPH oxidase (NOX)- and cyclooxygenases (COXs)-dependent oxidative stress pathways, and overexpression of the antioxidant enzyme glutathione peroxidase 1 (GPX-1) protects from age-dependent increased venous thrombosis." (PMID 32549393, 2020).